NPR1 (natriuretic peptide receptor 1)
Diseases named in the same sentence as NPR1 in open-access papers (continued):
Sharing a sentence is not in itself a finding about the gene and the disease.
fungal infection (8 papers, 2016 to 2022). "Because SA induces cotton resistance to fungal infection by activating NPR1, PR1 and PR5 expression, we further detected their gene expression levels." (PMID 35918649, 2022). "Modulation of the redox state of glutathione by GSTs regulates early signaling events in biotic stresses such as fungal infections, including activation of the essential regulator of systemic acquired resistance NPR1." (PMID 30157778, 2018). "Therefore, GhTCP4-like participates in a positive feedback regulation loop of SA biosynthesis via NPR1, increasing plant defenses against fungal infection." (PMID 35668804, 2022). "Therefore, it is possible that HSP24 physically interacts with NPR1 to stimulate the development of SAR against B. cinerea fungal infection in grape berries." (PMID 33763101, 2021). "The ectopic overexpression of the cotton (G. hirsutum) WRKY44 gene increases the resistance of Nicotiana benthamiana plants to fungal infections and activates the expression of PR genes, including PR1a, PR4, PR5, and NPR1." (PMID 34646290, 2021). "The SA regulated barley homologs of NPR1 and DIR1 exhibited increased accumulation in the 2Hb8 R NIL compared to M69 at 48 h after fungal infection." (PMID 27206761, 2016). "Mature green fruits (and not red ripe) are capable of SA-mediated response by NPR-1 (transcriptional co-regulator of SA responses and SA receptor in plants)-independent signaling pathway and can promote resistance to fruit against necrotrophic fungal infection." (PMID 34163503, 2021).
Obesity (8 papers, 2016 to 2025). Accumulation of substantial excess body fat. "Obesity-induced rats fed a high-fat diet have a lower NPR1/NPR3 ratio than the normal diet." (PMID 31817347, 2019). "In order to improve obesity, the NPR1/NPR3 ratio must be high in adipose tissue." (PMID 31817347, 2019). "Thus, an evident effect of obesity in modulation of ACE2 and NPR1 expression was demonstrated." (PMID 40806445, 2025).
ovarian carcinoma (8 papers, 2011 to 2025). A malignant neoplasm originating from the surface ovarian epithelium. "The high expression and signalling of NPR1 are important for tumour growth; its deficiency protects C57BL/6 from lung, skin and ovarian cancers." (PMID 32452127, 2020). "Studies reported that NPR1/gcy‐21 is the receptor for the cardiac hormone atrial natriuretic peptide, and it has been reported to be highly expressed in cancer cells such as lung cancer, prostate cancer and ovarian cancer." (PMID 32452127, 2020).
prostate carcinoma (8 papers, 2011 to 2025). A carcinoma that arises from epithelial cells of the prostate gland. "All this suggests that it is unlikely that JMJD2D impinges in a meaningful way on the oncogenic potential of prostate cancer cells through modulating the expression of GLIS3, RSPO3, NPR1 or OSR2." (PMID 38045004, 2023). "This would be consistent with the notion that methylation of JMJD2D could promote prostate cancer development through upregulation of CBLC and METTL27 as well as through downregulation of COL4A5, GLIS3, NPR1, OSR2, PLAGL1 and RSPO3." (PMID 38045004, 2023). "We also showed that PC3 cells, although expressing the NPs receptor NPR-1, express neither ANP nor BNP, suggesting that advanced stage prostate cancer cells cannot experience an autocrine NPs-mediate signaling for the control of inflammasome activation." (PMID 34070682, 2021).
atherosclerosis (6 papers, 2015 to 2023). A disease characterized by the build-up of fatty material and calcium deposition in the arterial wall resulting in partial or complete occlusion of the arterial lumen. "A previous study has reported that Npr1 deficiency increases the atherosclerotic plaque area in Apoe-knockout mice, indicating that NPR1 exacerbates the progress of atherosclerosis." (PMID 36293483, 2022). "To date, the underlying mechanism of NPR1 on the process of atherosclerosis remains undetermined." (PMID 36293483, 2022). "Furthermore, the atherosclerosis mouse model displays a decreased NPR1 and an increased ITGB4 expression." (PMID 36293483, 2022). "In conclusion, our findings demonstrate that NPR1 deficiency increases vascular endothelial cell adhesion by stimulating ITGB4 expression, which may contribute to the development of atherosclerosis." (PMID 36293483, 2022). "Genetic elements are of importance for the elevated risk of atherosclerosis and many genes have been implicated in the initiation and progression of atherosclerosis, including integrin beta 4 (ITGB4), intercellular adhesion molecule-1 (ICAM-1), and natriuretic peptide receptor 1 (NPR1)." (PMID 36293483, 2022). "Additionally, a reduced NPR1 and an increased ITGB4 expression level were found in an atherosclerosis mouse model." (PMID 36293483, 2022). "Thus, we further examined the expression of NPR1 and ITGB4 in the aorta from a mouse model of atherosclerosis." (PMID 36293483, 2022). "Notably, previous work has shown that atherosclerosis increases in an animal model lacking both NPR-A and ApoE (Npr1−/− ApoE−/− mice), suggesting that lack of NPR-A could induce VSMC growth through other receptor signaling, thus enhancing the negative vascular effects due to lack of ApoE." (PMID 26720342, 2015).
congestive heart failure (6 papers, 2012 to 2024). Failure of the heart to pump a sufficient amount of blood to meet the needs of the body tissues, resulting in tissue congestion and edema. "Mice carrying the global targeted disruption of Npr1 (encoding NPRA) exhibit a greatly increased incidence of congestive heart failure (CHF) and mortality." (PMID 36232788, 2022). "The variations in SNPs of Nppa, Nppb, and Npr1 in human patients seem to be associated with a family history of high BP and cardiovascular disorders, including myocardial infarction, cardiac mass, septal wall thickness, and congestive heart failure." (PMID 31416126, 2019). "TXGNN Explainer suggested that the relationship between NSIAD and amyl nitrite passes through AVPR2, congestive heart failure, and NPR1." (PMID 39148855, 2024). "Patients with congestive heart failure face similar fluid retention challenges, and congestive heart failure has been strongly associated with both AVPR2 and NPR1 genes." (PMID 39148855, 2024). "The complete systemic absence of Npr1 is associated with congestive heart failure (CHF) and sudden death after 6 months of age." (PMID 39109516, 2024).
breast carcinoma (5 papers, 2020 to 2025). "Moreover, survival analysis demonstrated that CD276 and NPR1 expression had a negative influence on OS and RFS of claudin-low subtype breast cancer." (PMID 36685583, 2022).
hypertensive heart disease (4 papers, 2009 to 2022). Abnormal enlargement of the heart resulting from long-standing hypertension. "Disruption of Npr1 encoding NPRA increases BP and causes hypertensive heart disease in null mutant mice; this heart disease is similar to that seen in patients with untreated hypertensive heart disease." (PMID 31416126, 2019). "Particularly, mice lacking a functional NPR1 gene coding for NPR-A have elevated blood pressures and hearts exhibiting marked hypertrophy with interstitial fibrosis resembling that seen in human hypertensive heart disease." (PMID 23372767, 2013).
renal fibrosis (4 papers, 2012 to 2023). A final common manifestation of a wide variety of chronic kidney diseases characterized by glomerulosclerosis and tubulointerstitial fibrosis. "However, in contrast to our KO strategy, several experimental findings have suggested that NPR1 KO mice primarily exhibit renal fibrosis, increased inflammation, and decreased function." (PMID 38026943, 2023).
Autoimmunity (3 papers, 2019 to 2023). The occurrence of an immune reaction against the organism's own cells or tissues. "Collectively, these data suggest that in unchallenged plants UBE4 suppresses the expression of SA-mediated NPR1 target genes and prevents autoimmunity, conceivably by altering the stability of upstream NLR immune receptors as well as the downstream NPR1 coactivator." (PMID 31589140, 2019). "Importantly, constitutive clearance of NPR1 from nuclei of resting cells by concerted action of CRL3 and the proteasome is necessary to prevent untimely activation of its target genes and associated autoimmunity." (PMID 31589140, 2019). "In resting cells, CRL3-mediated turnover of NPR1 is important for preventing autoimmunity in absence of pathogen threat." (PMID 31589140, 2019).
Insulin resistance (3 papers, 2022 to 2024). Increased resistance towards insulin, that is, diminished effectiveness of insulin in reducing blood glucose levels. "This whole-body insulin resistance was associated with a significantly reduced 2-DG uptake in various muscles of Npr1+/− mice." (PMID 39383215, 2024). "We here took advantage of two complementary mouse models (Nppa−/− and Npr1+/−) to critically examine the causal link between ANP/GCA deficiency and the development of insulin resistance, poor oxidative capacity, and T2D." (PMID 39383215, 2024). "As the causal effect of defective oxidative capacity in the development of insulin resistance remains controversial, we aimed to explore mitochondrial function in Npr1+/− mice before the onset of insulin resistance." (PMID 39383215, 2024). "Both Nppa−/− and Npr1+/− mice displayed hallmarks of insulin resistance and prediabetes." (PMID 39383215, 2024). "Despite similar body weight gain, mice injected with AAV-Cre developed systemic insulin resistance based on HOMA-IR, as well as clear signs of prediabetes, as previously observed in Nppa−/− and Npr1+/− mice." (PMID 39383215, 2024).
Intestinal infection (3 papers, 2019 to 2025). "Our study establishes that intestinal infection and bloating of the lumen, which depend on the virulence of P. aeruginosa, regulate both pathogen avoidance and aversive learning by modulating the neuroendocrine pathways NPR-1/GPCR and DAF-7/TGF-β that control aerotaxis behavior." (PMID 31674907, 2019). "To explore the impact of FAEW on neuroendocrine signaling related to intestinal infections and bloating, we examined the gene expression of key components in the serotonin biosynthesis pathway (tph‐1), the DAF‐7/TGF‐β pathway (daf‐7), and the NPR‐1/GPCR pathway (npr‐1, flp‐18, and flp‐21)." (PMID 40008431, 2025). "Because the DAF-7/TGF-β and NPR-1/GPCR pathways are induced by intestinal bloating and act synergistically to elicit pathogen avoidance, it is likely that animals integrate multiple inputs, including intestinal infection and chemosensation, to induce defense responses." (PMID 31674907, 2019). "Additionally, Intestinal infections and bloating, dependent on P. a virulence, regulate both pathogen avoidance and aversive learning through modulation of the DAF‐7/TGF‐β pathway and the NPR‐1/GPCR pathway, influencing chemotactic behavior and aversion learning." (PMID 40008431, 2025).
lymph node metastasis (3 papers, 2014 to 2025). "Clinical analysis reveals that elevated NPR1 protein level is correlated with increased lymph node metastasis and shorter patient survival." (PMID 40539884, 2025). "We pooled the NPR1 level of GC tissue with patients' clinicopathologic factors (age, sex, tumor size, tumor site, tumor differentiation, TNM stage, depth of tumor invasion, local lymph node metastasis, distant metastasis, and preoperative CEA) for statistical analysis." (PMID 33995640, 2021).
myocardial infarction (3 papers, 2019 to 2021). Gross necrosis of the myocardium, as a result of interruption of the blood supply to the area, as in coronary thrombosis. "Both ANP and BNP levels were elevated in the global Npr1–/– and haplotype Npr1+/– mice with myocardial infarction." (PMID 34489721, 2021).
autoimmune disease (2 papers, 2011 to 2025). A disorder resulting from loss of function or tissue destruction of an organ or multiple organs, arising from humoral or cellular immune responses of the individual to their own tissue constituents. "These insights pave the way for future research to explore the therapeutic potential of modulating the NPs/NPR1 axis in inflammatory and autoimmune diseases where DC subsets play important roles." (PMID 40643749, 2025). "Therefore, the newly discovered potent inhibitory action of NPs/NPR1-axis on IL-1β secretion in DCs suggest that the targeting of NPs/NPR1 axis could be a promising therapeutic approach for controlling excessive inflammation in autoimmune diseases and chronic inflammatory conditions." (PMID 40643749, 2025).
Cachexia (2 papers, 2019). Severe weight loss, wasting of muscle, loss of appetite, and general debility related to a chronic disease. "Given the high and prompt reduction of musclin expression in muscle during C26-induced cachexia, we measured the expression of its receptor Npr3 and the related ones, Npr1 and 2 by Q-PCR." (PMID 31614775, 2019). "Our data showing at later times increased expression of both Npr1 and 2 in cachectic TA of C26-carrying mice may suggest a possible compensatory activation of Npr1/2 axis during C26-induced cachexia." (PMID 31614775, 2019).
cardiac interstitial fibrosis (2 papers, 2022 to 2023). "Male Npr1 0-copy and 1-copy mutant mice treated with GW788388 showed attenuated levels of interstitial cardiac fibrosis by almost 65–70% (p < 0.001) in 0-copy and 40–45% (p < 0.001) in 1-copy male mice compared with untreated control mice." (PMID 36232788, 2022).
colitis (2 papers, 2022). Inflammation of the colon. "A decreased CD4+ T-cell population was restored after administration of 8-Br-cGMP, suggesting that Npr1 deficiency shifted T-cell population in the process of colitis." (PMID 35794311, 2022). "In sum, our findings highlight that loss of Npr1 possibly disturbs the immune response leading to colitis in the early life." (PMID 35794311, 2022). "Our data from two mouse models demonstrate that Npr1 deficiency causes a colonic inflammation phenotype accompanied with growth retardation, resembling pediatric onset colitis." (PMID 35794311, 2022). "Our data indicate that loss of Npr1 possibly interrupts immune response, which is critical to the pathogenesis of colitis in the early life." (PMID 35794311, 2022). "Thus, we decided to test the hypothesis that Npr1 deficiency impairs the immune system that further contributes to colitis in different models." (PMID 35794311, 2022). "To validate the involvement of Npr1 in colitis, we examined another mouse model induced by dextran sodium sulfate (DSS) and found a decreased Npr1 expression and shifted immune-cell populations as well." (PMID 35794311, 2022). "Administration of 8-Br-cGMP, a downstream activator of NPR1, restored these immune-cell populations disturbed in Npr1−/− mice and lessened the colitis-related phenotypes." (PMID 35794311, 2022). "When administrating PKG activator 8-Br-cGMP, the phenotype of colitis was attenuated in Npr1−/− and DSS mice." (PMID 35794311, 2022). "Here, we demonstrate in both Npr1−/− and DSS mouse models that loss of Npr1 disturbs the immune response with shifted population of immune cells, which causes experimental colitis during postnatal period." (PMID 35794311, 2022). "In this study, we found that null function of Npr1 disrupts the immune response that further leads to colitis in mice at the early life stages." (PMID 35794311, 2022). "These suggest that NPR1 regulates the immune response mediated by restructuring T-cell subpopulations to promote early development of colitis." (PMID 35794311, 2022). "Careful examination revealed unexpectedly that Npr1−/− mice developed colitis characterized by shortened colon, evident colonic mucosal damage, increased histopathological score, and higher colonic expression of proinflammatory cytokines interleukin-1B (IL1B) and -6 (IL6)." (PMID 35794311, 2022). "Next, we examined whether Npr1 contributes to the development of colitis in mice at the age of 4 weeks." (PMID 35794311, 2022). "All the data indicated that NPR1 may play a vital role in the experimental colitis." (PMID 35794311, 2022). "To validate NPR1 implicating in the colonic inflammation, we established DSS-induced colitis mouse model that is extensively used because of the most similarity to human ulcerative colitis." (PMID 35794311, 2022).
endothelial dysfunction (2 papers, 2022 to 2023). In vascular diseases, endothelial dysfunction is a systemic pathological state of the endothelium (the inner lining of blood vessels) and can be broadly defined as an imbalance between vasodilating and vasoconstricting substances produced by (or acting on) the endothelium. "Our recent study shows that NPR1 deficiency causes endothelial dysfunction marked by augmented interleukin 6 and interleukin 8, elevated reactive oxygen species (ROS) production, and decreased endothelial nitric oxide synthase (eNOS) and nitric oxide (NO) levels in vitro and in vivo." (PMID 36293483, 2022).
glioma (2 papers, 2020 to 2021). A benign or malignant brain and spinal cord tumor that arises from glial cells (astrocytes, oligodendrocytes, ependymal cells). "Our current study reveals presence of both natriuretic peptide guanylyl cyclase receptors (GC-A/Npr1 and GC-B/Npr2), in contrast to what we observed in C6 glioma cells." (PMID 33672024, 2021). "To confirm the expression and function of the natriuretic peptide system in C6 cells, we used multiplex RT-qPCR to examine the expression of Npr1, Npr2 and the glial cell marker, Gfap, in rat brain tissue and C6 glioma cells." (PMID 33672024, 2021). "We found that their homologous genes NPR1, DCAF4L2 and TSSK6 were highly expressed in glioma patients and patients with high NPR1 and TSSK6 predicted a short survival." (PMID 32452127, 2020). "Notably, the expression of homolog gene DCAF4L2/F47D12.9, TSSK6/W02B12.12 and NPR1/gcy‐21 was found to be higher in glioma compared with adjacent normal tissue." (PMID 32452127, 2020). "In addition, the high expression of TSSK6/W02B12.12 and NPR1/gcy‐21 correlated with a worse survival in glioma patients." (PMID 32452127, 2020). "Furthermore, we detected the NPR1 protein expression levels in glioma tissues." (PMID 32452127, 2020). "Next, we evaluated the prognostic values of NPR1, DCAF4L2 and TSSK6 in human glioma patients by Kaplan–Meier analysis." (PMID 32452127, 2020). "Using the TCGA data sets, we found that NPR1, DCAF4L2 and TSSK6 were overexpressed in glioma samples compared with adjacent normal tissues in human." (PMID 32452127, 2020). "Our results suggested NPR1/gcy‐21 and TSSK6/W02B12.12 might be potential targets for glioma therapy via suppressing tumour cell proliferation." (PMID 32452127, 2020). "Taken together, these results demonstrated that NPR1 and TSSK6 may be unfavourable prognostic factors and therapeutic targets for glioma patients." (PMID 32452127, 2020). "Notably, NPR1 and TSSK6 were highly correlated with the unfavourable prognosis of glioma patients and could be suitable prognostic indicators in glioma; these need to be confirmed by large clinical samples detection." (PMID 32452127, 2020).
Prostate tumor (2 papers, 2011 to 2023). "On the other hand, we focused on six genes (COL4A5, GLIS3, NPR1, OSR2, PLAGL1 and RSPO3) that were significantly downregulated in human prostate tumors as well as upregulated in DU145-R427 cells, suggesting that these genes might negatively interfere with prostate tumorigenesis." (PMID 38045004, 2023).
sarcoidosis (2 papers, 2020 to 2022). Sarcoidosis is a multisystemic disorder of unknown cause characterized by the formation of immune granulomas in involved organs. "The most dysregulated DEG identified in sarcoidosis tissues was NPR1, whose expression was markedly suppressed (> 7 fold reduced expression)." (PMID 36388923, 2022). "We have identified new genomic markers for sarcoidosis, ADAMTS1, CXCL2, and NPR1." (PMID 33276795, 2020). "Only six genes (ADAMTS1, HSPB6, NR4A1, CXCL2, NPR1, ITGA9) were exclusively dysregulated in both lung and lymph node in sarcoidosis granulomas but not in CM or TB." (PMID 33276795, 2020).